NEUROG3 (neurogenin 3)
Diseases named in the same sentence as NEUROG3 in open-access papers (continued):
Sharing a sentence is not in itself a finding about the gene and the disease.
teratocarcinoma (1 paper, 2016). A germ cell tumor characterized by the presence of an embryonal carcinoma component and a teratoma component. "Neurog3 also activated the Wnt9a gene in non-pancreatic cell contexts such as teratocarcinoma P19 cells and 3T3 fibroblasts, thus supporting the sufficiency of Neurog3 to increase Wnt9a expression in vitro." (PMID 26771085, 2016).
tumor (7 papers, 2013 to 2025). "Consistent with this, Neurog3 was shown to inhibit tumor cell proliferation and to promote the neuronal transdifferentiation of tumor cells both in vivo and in vitro." (PMID 41225636, 2025). "Genes implicated in embryonic and organ development, including SHH, NEUROG3, and MAFA, were downregulated, while immune-related genes like CCL2 and HAVCR2 were upregulated, suggesting immune modulation and alterations within the tumour microenvironment." (PMID 40683913, 2025).
infection (5 papers, 2008 to 2018). The state of being infected such as from the introduction of a foreign agent such as serum, vaccine, antigenic substance or organism. "We fractionated cells produced by Ad-RFP-Neurog3 infection by RFP intensity and measured mRNA expression of Neurog3, CHGA, SST and GHRL by qRT-PCR." (PMID 24252877, 2013). "Math6 mRNA was expressed at low levels in untreated mPAC cells and was induced 12 h after infection with AdCMV-NEUROG3, concomitantly with appearance of Pax4 mRNA and prior to induction of NeuroD1 mRNA, two known direct targets of Neurog3." (PMID 18560595, 2008). "Interestingly, Math6 mRNA expression declined 48 h post-infection, whereas levels of other Neurog3-induced mRNAs were maintained (Pax4, NeuroD1) or remained elevated (somatostatin) through 72 h." (PMID 18560595, 2008).
cancer (4 papers, 2017 to 2025). A tumor composed of atypical neoplastic, often pleomorphic cells that invade other tissues. "By reduced representation bisulfite sequencing (RRBS) analysis, we identified neurogenin-3 (Ngn3) as a bona fide target of ZEB1 implicated in the acquisition of cancer cell stemness." (PMID 28903350, 2017). "The neurogenin 3 gene (Ngn3) is a bona fide target of ZEB1, and its repression is a key factor contributing to ZEB1-induced cancer cell stemness." (PMID 28903350, 2017).
adenocarcinoma (1 paper, 2015). A common cancer characterized by the presence of malignant glandular cells. "Recently, Ding and co-workers reported that Tsc1 ablation mediated by Neurogenin 3-Cre (Neurog3Cre; Tsc1-/- mice) also induced “adenocarcinoma-like” lesions showing features of ACCs." (PMID 26683340, 2015).
gastrointestinal tumours (1 paper, 2021). "INSM1 and NEUROG3 are essential markers for pancreatic neuroendocrine tumours and have been implicated in gastrointestinal tumours, diarrhoea, and malabsorption." (PMID 33436826, 2021).
NEUROG3 also shares sentences with these, for which no sentence is quoted: Glucose intolerance (3 papers); Hypoglycemia (3); insulinoma (2); breast carcinoma (1); breast tumor (1); chronic pancreatitis (1); cleidocranial dysplasia (1); co-infection (1); colitis (1); Diarrhea (1); endocrine disorders (1); endometriosis (1); epilepsy (1); gastric cancer (1); Genetic obesity (1); Gestational Diabetes Mellitus (1); heart malformation (1); Hyperinsulinemia (1); hypogonadism (1); irritable bowel syndrome (1); medulloblastoma (1); microvillus inclusion disease (1); neonatal diabetes mellitus (1); pancreatic cell acinar carcinoma (1); pancreatic endocrine tumor (1); rectal cancer (1); Testicular atrophy (1); viral infection (1); vitamin A deficiency (1).